GCG (glucagon)
Diseases named in the same sentence as GCG in open-access papers (continued):
Sharing a sentence is not in itself a finding about the gene and the disease.
Hepatic steatosis (90 papers, 2012 to 2026). Steatosis is a term used to denote lipid accumulation within hepatocytes. "Initial studies suggest that such therapies can improve insulin secretion, assist pancreatic beta cell preservation and enhance insulin-mediated glucose metabolism while reducing glucagon secretion and risk of fatty liver disease." (PMID 41174263, 2026). "As a matter of fact, less heat release in Pai/Pai female mice may be related to hyperprostaglandinemia, hyperadrenerginemia and inflammatory response, while hyperglyceridemia and fatty liver are associated with hypercorticosteroidemia and glucagon resistance." (PMID 38816541, 2024). "Changes in glucagon sensitivity may contribute to weight‐loss independent improvements in hepatic steatosis following VSG." (PMID 37208943, 2023). "Furthermore, histology confirmed pronounced hepatic steatosis with the CDAHFD fed minipigs which is reported to cause reduced hepatic glucagon sensitivity in rats." (PMID 36456963, 2022). "Indeed, GCG antagonists, developed as potential glucose-lowering therapies, were associated with an increase in hepatic steatosis, suggesting that GCG agonists may reduce hepatic steatosis." (PMID 40741227, 2025). "Survodutide’s dual glucagon/GLP-1 receptor agonism reduces hepatic steatosis and circulating IL-1β levels in phase III NASH trials, while oral GLP-1 RAs like orforglipron circumvent injection barriers without compromising anti-inflammatory efficacy." (PMID 40699756, 2025). "SGLT2-is also appear to act on pancreatic α-cells, leading to an increase in glucagon secretion, which promotes β-oxidation of fatty acids, and consequently, reduces liver triglycerides and improves liver steatosis." (PMID 39897209, 2025). "In contrast, human studies in individuals with hepatic steatosis have shown that baseline hepatic mitochondrial function is relatively preserved and can be significantly enhanced by glucagon stimulation." (PMID 40822953, 2025). "It ameliorated hepatic steatosis by enhancing fatty acid oxidation, stimulating glucagon secretion, and suppressing DNL, while also improving mitochondrial function." (PMID 41171838, 2025). "Its infusion at rates >5 mg/kg/min and elevated molar ratio of portal venous insulin to glucagon due to the PN administration with high glucose concentration seem to induce hepatic steatosis." (PMID 40284236, 2025). "Among these, hepatic steatosis—which is highly prevalent in obese pediatric patients—likely plays a pivotal role in promoting hepatic glucagon resistance." (PMID 41149695, 2025). "This corroborates the theory of a link between hepatic steatosis, glucagon concentrations, and amino acid levels and fits well with the liver–alpha cell axis concept." (PMID 38276866, 2024). "Our data also show that dietary protein content can dramatically influence some aspects of chronic glucagon biology in mice, and others have shown that hepatic steatosis can influence glucagon sensitivity." (PMID 39236784, 2024). "Concurrently, treatment with cotadutide led to reduction of hepatic steatosis and ameliorated mitochondrial turnover and function in a direct GCG-dependent mechanism of action, as observed in the DIO mouse model." (PMID 38612640, 2024). "Hepatic steatosis, glucose tolerance, insulin and glucagon resistance, and hepatic transcriptomics were investigated at the end of the study period and treatment groups were compared with mice undergoing sham surgery only (Sham‐Ad lib)." (PMID 37208943, 2023). "GLP-1 can increase insulin release, decrease glucagon secretion, reduce hepatic steatosis, and improve hepatic fibrosis." (PMID 35770089, 2022). "Hepatic steatosis can lead to glucagon resistance, wherein glucagon‐induced amino acid metabolism is impaired, causing elevated plasma levels amino acids and hence also glucagon." (PMID 34713962, 2022).
Hepatic steatosis (continued). "Increased liver steatosis the enriched glucagon-signaling pathway, adipocytokine signaling pathway, insulin resistance in the liverdecrease in the genus Turicibacter in the gut." (PMID 33918456, 2021). "Previous research found that PAE significantly decreased serum insulin and glucagon levels, improved insulin sensitivity and serum lipids profiles, and alleviated hepatic steatosis in Sprague-Dawley rats." (PMID 33638949, 2021). "Oral administration of A. actinomycetemcomitans increased liver steatosis and enriched glucagon signaling pathway, adipocytokine signaling pathway, and insulin resistance in the liver." (PMID 33918456, 2021). "Other groups have explored the concept of GLP-1/GIP/glucagon triagonism to obtain extra benefits from adding the benefits of glucagon action (promotion of energy expenditure and amelioration of fatty liver disease) to the ‘twincretin’ effects of GLP-1 and GIP." (PMID 32436022, 2020). "In contrast, studies in animal models of hepatic steatosis have reported an attenuated effect of glucagon on glucose production thereby possibly linking pathophysiological traits of the liver to glucagon resistance." (PMID 31284506, 2019). "The results showed that paeoniflorin significantly decreased serum insulin and glucagon levels, improved insulin sensitivity and serum lipids profiles, and alleviated hepatic steatosis in fructose-fed rats." (PMID 30081580, 2018). "We found that glucagon and olaparib partially prevented the development of fatty liver disease following an overload of fatty free acids in the medium." (PMID 30250238, 2018). "Such binding reduces gastric emptying and food intake, inhibits the production of postprandial glucagon, and thereby suppresses the progression of fatty liver disease in patients with T2DM." (PMID 30473540, 2018). "Since glucagon stimulates lipolysis and reduces lipogenesis, glucagon was proposed as a therapy option for hepatic steatosis." (PMID 27973438, 2016). "Subsequently, the released plasma glucagon levels induce β-oxidation, which stimulates fatty acid oxidation instead of carbohydrate oxidation reducing the liver triglyceride content and producing improvement of hepatic steatosis." (PMID 40085410, 2025). "In addition, these effects are mediated independently of long-term changes in food intake or body fat mass; changes in serum triglyceride or plasma glucagon levels; or improvements in either glucose tolerance or hepatic steatosis." (PMID 40371641, 2025). "In NAFLD, hyperglucagonemia is attributed to glucagon resistance induced by hepatic steatosis." (PMID 40069760, 2025). "This rise in glucagon may represent a metabolic response to prevent hepatic steatosis, as glucagon increases have been previously shown to induce hepatic fat oxidation." (PMID 39599691, 2024). "Both fatty liver and insulin resistance correlate well with glucagon levels in plasma." (PMID 37764697, 2023). "Since glucagon reduces liver fat by decreasing de novo lipogenesis and increasing fatty acid oxidation, glucagon resistance may exacerbate hepatic steatosis." (PMID 37208943, 2023). "Moreover, glucagon increases fat oxidation and there is interest in its effects in ameliorating fatty liver disease." (PMID 32436022, 2020). "Furthermore, in patients with T2DM and fatty liver, the signal transduction for glucagon is dysfunctional in the liver leading to impaired ureagenesis and deranged amino acid levels." (PMID 28634585, 2017). "Furthermore, hepatic steatosis may impair the glucagon-dependent enhancement of AA catabolism in mice and humans by NAFLD." (PMID 37764697, 2023). "Hyperglucagonemia appears to be a pathophysiological consequence of hepatic steatosis, thus, the hypothesis of the study is that hepatic fat accumulation leads to increased insulin resistance and impaired glucagon metabolism leading to hyperglucagonemia in pediatric NAFLD." (PMID 36133310, 2022).
Hepatic steatosis (continued). "Hypothesis was that hepatic insulin resistance (secondary to hepatic steatosis) via defective glucagon signaling/ glucagon resistance would lead to impaired ureagenesis and, hence, increased plasma concentrations of glucagonotropic amino acids and, subsequently, glucagon." (PMID 36686477, 2022). "Moreover, the metabolic effects of glucagon contribute to hepatic fat clearance in fatty liver disease models, suggesting glucagon-induced depletion of lipid stores may reduce viability in liver cancer cells that demand more fatty acids for growth." (PMID 35123542, 2022). "Furthermore, hepatic steatosis may impair glucagon-dependent enhancement of amino acid catabolism, as demonstrated by the three GcgrV369M+/+ mice with liver steatosis and high amino acid levels." (PMID 34002801, 2021). "During DPP4 deficiency (inhibition or a knockout in mice), the sensitivity of pancreatic β-cells to this hormone may diminish, and as a result, insulin secretion may decrease, which, along with the action of glucagon and fatty liver disease, raises blood glucose levels." (PMID 33228030, 2020). "Importantly, hyperglucagonemia seems to be associated with a fatty liver rather than with diabetes per se, and plasma concentrations of glucagon and non-branched-chain amino acids are characteristically increased in subjects with increased liver fat (as reflected by elevated HOMA-IR levels)." (PMID 33333850, 2020). "When administered a glucagon/GLP-1 receptor co-agonist, type 2 diabetic and obese rodents displayed reduced hepatic steatosis, increased hormone-sensitive lipase (HSL) activity in adipocytes, and improved dyslipidemia." (PMID 31284506, 2019). "It has been observed that the liver becomes insensitive to glucagon as a result of hepatic steatosis in NAFLD patients, which further promotes glucagon secretion." (PMID 30995792, 2019). "In contrast, TIX100 decreases alpha cell glucagon secretion and serum glucagon levels and protects against hepatic steatosis without an increase in alpha cells or elevation in liver transaminases." (PMID 39429740, 2024). "Further effective treatment strategies are clearly needed, and gut-derived hormones (like glucagon, GIP, etc.)as well as several neuropeptides may carry a potential to influence liver steatosis due to their food intake and energy-regulating characteristics." (PMID 38542814, 2024). "Two recent studies from our group have found support of a glucagon-alanine index that captures the lack of glucagon-induced ureagenesis, which seems to be specifically impaired in patients with hepatic steatosis and fibrosis." (PMID 31284506, 2019). "However, in this state, the biological effect of glucagon is weakened, and the impact of glucagon on SIRT1 is also impaired, while SIRT1 can inhibit hepatic steatosis and inflammatory responses to hepatic metabolic disorders." (PMID 30995792, 2019). "Taken together, these findings may have clinical implications for therapeutic strategies to use glucagon to activate the cAMP signaling molecule CREBH and increase hepatic Insig-2a abundance in the treatment of hepatic steatosis and hyperlipidemia." (PMID 27582413, 2016). "Interestingly, chronic administration of the glucagon/GLP-1 agonist in diet-induced obese (DIO) mice was able to reverse obesity, to improve hepatic steatosis and glucose tolerance, to increase metabolic rate, to decrease body fat mass, to reduce feeding, and to increase energy expenditure." (PMID 31337027, 2019). "As elevations in plasma glucagon are a reported consequence of intra-hepatic fat deposition, future prospective studies examining the role of glucagon on ICR in well described cohorts of people with and without hepatic steatosis are warranted." (PMID 39138690, 2024).
metabolic syndrome (83 papers, 2007 to 2026). A cluster of metabolic risk factors for CARDIOVASCULAR DISEASES and TYPE 2 DIABETES MELLITUS. "Instead, we analyzed the relationship between metabolic syndrome and glucagon to insulin ratio, which are strongly associated with cardiovascular disease in patients with T2DM." (PMID 37762748, 2023). "We investigated the association between glucagon to insulin ratio and metabolic syndrome in patients with T2DM." (PMID 37762748, 2023). "Defects in insulin release, typical of T1DM and the animal model used, imbalance the release of glucagon, corticosteroids, and catecholamines and predispose to dyslipidemia and diabetic ketoacidosis." (PMID 30517288, 2018). "Building upon traditional risk factors (such as hypertension and dyslipidemia), incorporating glucagon level assessment might enable more precise risk stratification." (PMID 41458542, 2025). "Simultaneously, when high doses of t10c12 are used, it can specifically result in an increased PEG2, which probably induces increases in corticosterone and glucagon, and the combination of these factors causes metabolic syndrome, including fatty liver and hyperglyceridemia in female mice." (PMID 38816541, 2024). "This suggests that glucagon-targeted therapeutics may reduce cardiovascular risk by improving metabolic syndrome." (PMID 37762748, 2023). "Thus, analyzing the association between the glucagon to insulin ratio and metabolic syndrome in patients with T2DM would indirectly shed light on the effect of glucagon on cardiovascular disease." (PMID 37762748, 2023). "Similarly, cobalt has also been associated with improved glucose tolerance, glucagon signaling suppression, and amelioration of dyslipidemia factors." (PMID 37242230, 2023). "According to this concept, fat deposition in the liver, a hallmark of the metabolic syndrome, might impair hepatic glucagon signalling." (PMID 33275161, 2021). "While therapeutic targeting of the glucagon pathway holds promise, clinical challenges such as dyslipidemia, hepatic stress, and amino acid imbalance must be carefully addressed." (PMID 40822953, 2025). "Anti-regulatory hormones such as catecholamine neurotransmitters and glucagon, which are activated during psychological stress and metabolic syndrome, can lead to disturbances in glucolipid metabolism and abdominal obesity." (PMID 38388343, 2024). "The glucagon to insulin ratio was a significant predictor of metabolic syndrome even after adjusting for confounders through multiple regression analysis." (PMID 37762748, 2023). "In this investigation, a higher number of metabolic syndrome components correlated with an elevated glucagon to insulin ratio." (PMID 37762748, 2023). "The effects of the glucagon to insulin ratio on the presence of metabolic syndrome among patients with DM were analyzed using hierarchical logistic regression." (PMID 37762748, 2023). "The fasting glucagon to insulin ratio was significantly lowered as the number of metabolic syndrome components increased." (PMID 37762748, 2023). "The fasting glucagon to insulin ratio was significantly lower in patients with metabolic syndrome (14.0 ± 9.7 vs. 17.3 ± 10.3, p < 0.05)." (PMID 37762748, 2023). "In hierarchical logistic regression analysis, the fasting glucagon to insulin ratio significantly contributed to metabolic syndrome even after adjusting for other covariates." (PMID 37762748, 2023). "The fasting glucagon to insulin ratio significantly decreased with increasing metabolic syndrome components." (PMID 37762748, 2023). "In our study, individuals with metabolic syndrome had a significantly lower glucagon to insulin ratio." (PMID 37762748, 2023). "In this study, the metabolic syndrome group had a significantly lower glucagon to insulin ratio, and the glucagon to insulin ratio significantly decreased with an increasing number of metabolic syndrome components." (PMID 37762748, 2023).
metabolic syndrome (continued). "In the present study, the glucagon to insulin ratio was significantly lower in patients with T2DM who also have metabolic syndrome." (PMID 37762748, 2023). "The glucagon to insulin ratio remained a predictor of metabolic syndrome even after adjusting for several factors." (PMID 37762748, 2023). "Fasting and postprandial glucagon concentrations did not significantly differ between the two groups, but the fasting glucagon to insulin ratio was significantly lower in the metabolic syndrome group." (PMID 37762748, 2023). "Some of these well-known pathways, such as the PPAR, FoxO, adipocytokine, and glucagon signaling pathways, were found to play essential roles in metabolic syndrome." (PMID 35321016, 2022). "Previously, we reported evidence showing that chronic cola consumption in rats impairs pancreatic metabolism of insulin and glucagon and produces some alterations typically observed in the metabolic syndrome, with an increase in oxidative stress." (PMID 34115756, 2021). "Pathogenesis of metabolic syndrome proceeds from the dysregulation of any of these four processes in glucagon/insulin physiology." (PMID 35002748, 2021). "In preclinical studies, these agents improve steatosis and dyslipidemia, possibly as a consequence of regulation of hepatic lipid metabolism by glucagon agonism." (PMID 31068828, 2019). "IR is an important component of the metabolic syndrome and precedes the secretion of glucagon." (PMID 38273418, 2024). "Furthermore, the glucagon to insulin ratio dropped considerably with the rise in the number of metabolic syndrome elements." (PMID 37762748, 2023). "The glucagon to insulin ratio was identified as a significant predictor of metabolic syndrome." (PMID 37762748, 2023). "Likewise, cobalt also plays essential roles in glucose and lipid metabolisms by improving tolerance to glucose, regulating glycogen depots via suppressing glucagon signaling, and ameliorating dyslipidemia." (PMID 36552647, 2022). "Copeptin, the c-terminal portion of arginine vasopressin, which may be related to metabolic syndrome through altering insulin and glucagon secretion, was determined in this study." (PMID 36320894, 2022). "They tightly control insulin release, glucagon secretion, hepatic gluconeogenesis, and glycogenolysis, and elevated levels of these catecholamines are related to metabolic dysregulation and metabolic syndrome." (PMID 33335492, 2020). "In this sense, derangements of α-cells at early age might precede the development of dyslipidemia with ageing in Wistar rats, as suggested in early and recent studies regarding the role of glucagon on lipid metabolism." (PMID 31405194, 2019). "Antipsychotics apparently also stimulate glucagon secretion in the pancreatic α-cells, resulting in excessive glucose production in the liver even when the peripheral glucose levels are high, and they later develop metabolic syndrome in persons with schizophrenia." (PMID 35806096, 2022). "Indeed, we could not rule out the possibility that some key parameters, such as glucose, insulin, and glucagon, may attenuate the relationship between the ANGPTL4 and SUA-associated dyslipidemia." (PMID 35711366, 2022). "Indeed, the use of Glucagon/T3 in obese mice ameliorates serum dyslipidemia, diminishes adipose mass, reverses NASH, reduces atherosclerotic plaque accumulation, and improves glucose metabolism, while avoiding thyrotoxicosis and the diabetogenic effects of glucagon." (PMID 32733906, 2020). "Furthermore, glucagon and thyroid hormone effects have been combined in a conjugate that corrected dyslipidemia in several diet-induced obese rodent models, demonstrating their lipid and weight lowering effects, being partially dependent on increased thermogenesis." (PMID 31337027, 2019).